ACE (angiotensin I converting enzyme)
Diseases named in the same sentence as ACE in open-access papers (continued):
Sharing a sentence is not in itself a finding about the gene and the disease.
asthma (continued). "Additional implication of a potential role of ACE in asthma comes from analysis of an ACE insertion/deletion (I/D) polymorphism in different asthmatic populations." (PMID 20011602, 2009). "In specialist clinics chronic cough occurs in association with asthma, rhinitis, gastro-oesophageal reflux (GERD), and ACE inhibitor use." (PMID 18673583, 2008). "Risk factors for this condition include menopause, individuals with a history of migraine, osteoporosis, asthma and angiotensin-converting enzyme (ACE) inhibitor therapy and individuals with an elevated intracast pressure due to a tight case or extreme positions." (PMID 28127572, 2017). "After subgroup analysis by age, the ACE D/I, β2-Adrenergic Receptor (β2-AR) -79G/C, TNF-α -308G/A, Interleukin 4 receptor(IL-4R) -1902G/A and IL-13 -1923C/T polymorphisms were found significantly associated with asthma risk in Chinese children." (PMID 20868478, 2010). "In addition, the ACE D/I, FcεRIβ -6843G/A, TNF-α -308G/A, IL-13 -1923C/T and IL-13 -2044A/G polymorphisms were associated with asthma risk in Chinese adults." (PMID 20868478, 2010). "Extrathoracic airway hyperresponsiveness is another manifestation of laryngeal dysfunction and has been reported in several conditions where cough is prominent, such as rhinosinusitis, ACE inhibitor cough, gastroesophageal reflux, and patients with asthma-like symptoms." (PMID 19292930, 2009). "There are plausible potential mechanisms by which elevated blood ACE might promote features of asthma pathology." (PMID 20011602, 2009). "Regard rs4309 of ACE, in the comparison AERD vs. (HC or asthma) the result was statistically significant after Bonferroni correction (factor of 311), p = 0.03 in both comparisons." (PMID 30254660, 2018). "Fevipiprant, which targets PTGDR2, has been evaluated in clinical trials for asthma and atopic dermatitis; Zileuton, a 5-lipoxygenase inhibitor that reduces leukotriene synthesis, targets ALOX5; and captopril, an angiotensin-converting enzyme inhibitor, targets ACE." (PMID 41395465, 2025). "In non-smoking patients with normal chest X-rays who are not taking ACE inhibitors, chronic cough is determined in 86% of cases by asthma, postnasal drip syndrome (PNDS), and GERD, although often multiple causes co-exist in a single patient." (PMID 32784573, 2020). "For TBXAS1 rs757760, MS4A2 rs502581, IL10 rs3024498, and ACE (rs4293 and rs4309), we did not detect any statistical association comparing AERD vs. asthma/HC or asthma vs. HC, in the allelic, recessive and codominant models (p > 0.05)." (PMID 30254660, 2018). "Co-factors, or augmenting factors, such as concomitant asthma, exercise, or specific drugs (e.g., non-steroidal anti-inflammatory drugs, ACE inhibitors), must always be considered." (PMID 29238519, 2017). "The presence of one or more of these symptoms for at least six weeks in the absence of LPRD, allergy, asthma, ACE inhibitor intake, and psychogenic disorder was defined as LSN." (PMID 23818901, 2013). "EAHR is a feature of cough due to ACE inhibitor use, rhinosinusitis and GERD, and possibly asthma." (PMID 18673583, 2008). "The most common causes of chronic cough in non-smoking patients with normal chest radiographs, who are not on angiotensin converting enzyme (ACE) inhibitors are post nasal drip syndrome (PNDS), asthma, gastroesophageal reflux and chronic bronchitis." (PMID 32456613, 2020). "It is considered in the differential diagnosis of chronic cough (longer than 6 weeks), when conditions such as asthma, pneumonia, bronchitis, LPR, or ACE inhibitor adverse reactions have been ruled out." (PMID 23818901, 2013).
anemia (68 papers, 2006 to 2026). A reduction in the number of red blood cells, the amount of hemoglobin, and/or the volume of packed red blood cells. "Anemia was also significantly associated with the use of ACE inhibitors (p = 0.042), AT1 receptor antagonists (p = 0.012), beta-blockers (p = 0.023), and diuretics (p = 0.006)." (PMID 40647671, 2025). "Anemia, although of transient nature, was present as well, resembling three cases with pathogenic variants in ACE." (PMID 33768328, 2021). "In our elderly patients, contrast-induced nephropathy is enhanced by the frequent association of preoperative anaemia and ACE-inhibitors therapy, as well as CPB time." (PMID 33113315, 2021). "ACE inhibitor-associated anemia is due to the suppression of erythropoietin production, in response to A-acetyl-seryl-aspartyl-lysyl-proline accumulation in plasma." (PMID 31655853, 2020). "The use of ACE inhibitors decreases hematocrit levels, which lowers the circulating angiotensin II, further inhibiting the growth of erythroid progenitors and N-acetyl-seryl-aspartyl-proline catabolism, causing anemia in the first 3 months of therapy." (PMID 37374094, 2023). "Furthermore, anemia is common in HF patients due to inflammation, iron deficiency, kidney disease, and use of ACE inhibitors." (PMID 32537050, 2020). "The use of angiotensin-converting-enzyme (ACE) the inhibitors also plays a role in causing anemia." (PMID 23213342, 2012). "Finally, the results indicate that the iron deficiency is driven by hepcidin accumulation in blood due to decreased GFR.There were several reports in which anemia has been demonstrated in RAS-deficient mice including ACE knockout, Agt-KO, renin knockout, and double AT1aR/AT1bR receptor knockout." (PMID 39869503, 2025). "A single study quantified plasma iron levels in ACE-KO mice; this was the first report to demonstrate anemia in such animals." (PMID 39869503, 2025). "Optimizing disease management requires a multifaceted strategy that includes hydroxychloroquine, ACE inhibitors, and treating consequences, including severe anemia." (PMID 38975413, 2024). "Anemia was also more likely with therapy involving angiotensin-converting enzyme (ACE) inhibitors, angiotensin II receptor antagonists, mycophenolate mofetil, or azathioprine." (PMID 38138933, 2023). "Regarding nutritional anemia, it is possible that anemia cases in patients taking ACE inhibitors are assumed to be due to the known side effect of the medication and therefore not coded as nutritional." (PMID 35689299, 2022). "ACE inhibitors would appear protective against nutritional anemia when in reality ACE inhibitors only affect its coding." (PMID 35689299, 2022). "Preoperative correction of anaemia, discontinuation of ACE inhibitors and surgical techniques reducing CPB time would contribute significantly to decreased postoperative AKI prevalence." (PMID 33113315, 2021). "Her anemia worsens with an ACE inhibitor, initiated to reduce proteinuria and limit GFR decline, so it was discontinued." (PMID 30305036, 2018). "ERT has been proven safe and effective for visceromegaly, anemia, thrombocytopenia, and skeletal symptoms related to GD, and it reduces the blood levels of the acid phosphatase, ACE, and chitotriosidase biomarkers." (PMID 28506293, 2017). "Anemia in ACE knockout mice can be recovered by infusion of a small dose of Ang II, which has not yet been tested in Agt(-/-) mice." (PMID 26107632, 2015). "A similar anemia was also present in another strain of genetically engineered mice expressing a truncated form of secreted ACE." (PMID 24167502, 2013). "Anemia is a key side effect of ACE inhibitors, developing through two primary mechanisms." (PMID 41012833, 2025). "Moreover, deletional mutations in the ACE and AGTR1 genes encoding the human ACE and AT1R, respectively, lead to anemia in humans demonstrating a conserved role." (PMID 39869503, 2025).
anemia (continued). "Additionally, they had higher usage of ACE inhibitors, AT1 antagonists, and beta-blockers, suggesting that patients with greater clinical severity are more susceptible to anemia." (PMID 40647671, 2025). "Thesefactors may be the cause of increased cardiovascular risk and all-cause death.Fifth, studies indicated that the use of angiotensin-converting enzyme (ACE) inhibitors can depress the synthesisof erythropoietin, which can aggravate anemia." (PMID 39077655, 2024). "It is known that the activation of renin-angiotensin system enhances the erythropoietin productions, while its inhibition due to ACE inhibitors may exacerbate anaemia." (PMID 31521117, 2019). "Similar to the previous result obtained in ACE knockout mice, these results indicate that the absence of Ang II is associated with anemia as well as hypotension in Agt(-/-)." (PMID 26107632, 2015). "To date, several other possible explanations for anemia have been proposed, such as direct apoptotic effects of ACEi on erythroid precursor cells, drug toxicity, and accumulation of substrates of renin or ACE." (PMID 26107632, 2015). "Similarly, administration of ACE inhibitors reduces plasma erythropoietin levels, exacerbating anemia." (PMID 24167502, 2013). "The hematocrit level was corrected in ACE-deficient mice to near wild-type levels, strongly suggesting that the lack of A-II in these mice was the direct cause of the anemia." (PMID 24167502, 2013). "Interestingly, the ACE KO mice develop mild anemia and ACE inhibitors and AT1R antagonists are sporadic reported to cause anemia and bone marrow aplasia." (PMID 22200760, 2012). "ACE inhibitors should be considered in the differential diagnosis in patients with nonspecific systemic inflammation and anaemia of chronic disease where no other cause is found." (PMID 22937315, 2011). "However, the ACE inhibition has disadvantage roles such as, allowing fast intense inflammatory response, compromised oxygen transport to tissues, leading to hypoxia and an impaired cell metabolism in a situation of severe anaemia." (PMID 31234939, 2019). "Initial labs demonstrated anemia (Hb 94 g/L), hypoalbuminemia (25-30 g/L), markedly raised C-reactive Protein (CRP) (91-110 mg/L), and elevated angiotensin-converting enzyme (ACE) (92 U/L), suggesting systemic inflammation and possible granulomatous disease." (PMID 41450390, 2025). "Debate is still on-going regarding the potential effects of renin-angiotensin system inhibitors, such as angiotensin-converting enzyme (ACE) inhibitors or angiotensin II-receptor antagonists (ARBs), on the development of anaemia in patients with renal disease." (PMID 31521117, 2019). "However, the study participants had low ejection fraction, were followed for only 12 months and the study did not focus on incident ACE inhibitor therapy, raising the possibility of reverse causality or the presence of residual confounders (e.g. anemia, as hemoglobin data was not available)." (PMID 21917174, 2011). "Deficiency in ACE due to ACE inhibition or complete absence of ACE due to genetic manipulation or mutations also leads to severe disease phenotypes including defects in fetal development, hypotension, inability to concentrate urine, structural renal defects, anemia, and reduced male fertility." (PMID 20454656, 2010). "The loss of the RUV in HD was an independent predictor of all-cause of mortality, in parallel with the unsecured financing HD, hypervolemia, anemia, absence of ACE inhibitor or betablocker, presence of catheter as a vascular access and hypoalbuminemia." (PMID 27871253, 2016). "The loss of residual urine volume, financing not secured of HD, hypervolemia, not taking ACE inhibitor and betablocker, central line catheter as a vascular access normal serum albumin levels and anemia have emerged as the main independent predictors of all-cause mortality in this study." (PMID 27871253, 2016).
breast carcinoma (67 papers, 2008 to 2025). "Due to the critical role of ACE in the synthesis of Ang II, it has been shown that reduced ACE levels or the use of ACE inhibitors lowers the risk of breast cancer by 50%." (PMID 40149544, 2025). "A candidate gene approach has discovered about 70 genes to be associated with preeclampsia and some of the genes overlap with the breast cancer susceptibility genes such as ACE, VEGF, IGF1R and FLT1." (PMID 29361985, 2018). "There was a significant association between the intake frequency of green tea and the decrease in risk of breast cancer among women with high-activity of the angiotensin-converting enzyme (ACE) genotype." (PMID 27483305, 2016). "Among women with high-activity of the angiotensin-converting enzyme (ACE) genotype, green tea intake frequency significantly decreased the risk of breast cancer (p = 0.039)." (PMID 27483305, 2016). "Similarly, a significant reduction in breast cancer risk was observed among women exposed to the highest cumulative doses of ACE inhibitors combined with aspirin." (PMID 39857949, 2025). "Clinical strategies have been implemented to counteract cardiovascular risk factors in breast cancer survivors including modifications in treatments, monitoring of symptoms, and pharmacological strategies (i.e., beta-blockers, angiotensin-converting enzyme (ACE)-inhibitors, etc.)." (PMID 37715884, 2023). "This hypothesis was confirmed by studies demonstrating a marked increase in incidence of breast cancer in women carrying D/D allele of the ACE gene, which is linked to higher levels of the circulating ACE isoform in blood of these patients." (PMID 22581182, 2012). "Neutrophils acquire anti-tumor phenotypes in breast cancer under the influence of ACE inhibitors and AGTR1 antagonists, thereby suppressing tumor growth." (PMID 40564191, 2025). "The novelty of this study lies in the reduction of worsening of RV function in breast cancer patients who had a treatment with ACE inhibitors or β‐blockers or both, concomitant with the chemotherapy." (PMID 40965835, 2025). "Whilst ACE inhibitors and ARBs have been proposed to affect breast cancer through their impact on the renin‐angiotensin system, meta‐analyses across smaller studies are inconsistent." (PMID 41163361, 2025). "A recent study showed that in normal breast tissue, the elements of ACE-2/Ang1–7/Mas receptor pathway were predominantly expressed, while in breast cancer tissue, the ACE/Ang II/AT1 receptor pathway was activated prominently." (PMID 38831897, 2024). "The protective effect of ACE inhibitors in lessening adipocyte inflammation in breast cancer cells was increased with EPA." (PMID 36973648, 2023). "The PROACT trial will establish the effectiveness of the ACE inhibitor enalapril maleate (enalapril) in preventing cardiotoxicity in patients with breast cancer and non-Hodgkin’s lymphoma (NHL) receiving anthracycline-based chemotherapy." (PMID 36585130, 2022). "ACE gene expression in breast basal-like tumor samples was significantly lower than that in all other breast cancer subtypes except luminal B subtype." (PMID 33858332, 2021). "In normal breast tissue, RAS activity mainly relies on the alternative pathway (ACE-2/Ang 1-7/MASR), whilst in breast cancer tissue, the classical pathway (ACE/Ang II/AT1R) was the prominent." (PMID 34539580, 2021). "High ACE expression reduces overall survival in breast cancer patients, while high ACE-2 expression improves cancer prognosis and is associated with low metastatic potential of breast cancer." (PMID 34539580, 2021). "18F-FDG micro PET was used to monitor the therapeutic effect of ACE andvincristine in the DMBA-induced breast cancer model." (PMID 31826147, 2019). "Our findings suggest that ACE has a protective effect against DMBA-inducedoxidative stress in breast cancer tissues." (PMID 31826147, 2019).
breast carcinoma (continued). "In breast cancer patients, there is emerging evidence for prescribing beta-blockers or angiotensin converting enzyme (ACE) inhibitors upfront in patients receiving chemotherapy and/or trastuzumab for prevention of CTRCD." (PMID 32154018, 2019). "Our results show that ACE prevents TNFα-induced migration of MDA-MB-231 metastatic breast cancer cells and inhibits TNFα-induced CXCR3 and CXCL10 expression through inhibition of the IκB kinase (IKK)-mediated NF-κB pathway." (PMID 30177620, 2018). "A recent report demonstrated that favorable effects of ACE inhibitors and BBs on preventing cardiotoxicity and improving survival of breast cancer patients treated with trastuzumab and/or anthracyclines." (PMID 29473044, 2018). "Our results suggest that ACE has potential as a herbal supplement for the inhibition of breast cancer metastasis." (PMID 30177620, 2018). "Until now, the vast majority of the studies on cardioprotection have been performed mostly on anthracyclines and, in the case of breast cancer, on anthracyclines + trastuzumab and have been proposing dexrazoxane, ACE inhibitors, and statins." (PMID 26583088, 2015). "The ACE inhibitor captopril has been shown to inhibit proliferation of a variety of cell types, including human breast cancer, and to reduce tumor growth in experimental models of cancer." (PMID 19061507, 2008). "Angiotensin-converting enzyme (ACE) activity was also investigated in patients with breast cancer and was elevated in women in complete remission in both cases comparing the values with normal controls." (PMID 18665244, 2008). "In terms of cancer, genetically proxied ACE inhibitors were found to increase the risk of colorectal cancer, but they did not appear to affect the risk of breast cancer, lung cancer, or prostate cancer." (PMID 39567981, 2024). "Clinically, breast cancer patients with cardiac dysfunction and arrhythmias are often monitored and intervened during the treatment, such as application of angiotensin-converting-enzyme (ACE) inhibitors or beta-blockers." (PMID 35402243, 2022). "Early data suggest that aggressive use of β blockers and ACE inhibitors may allow safe continuation of trastuzumab therapy in breast cancer patients with treatment-emergent mild LVD." (PMID 33766148, 2021). "ACE inhibitors and BB were associated with increased cardiotoxicity-free survival and fewer interruptions in cancer therapy compared to placebo among HER2 positive breast cancer patients treated with trastuzumab (± anthracyclines)." (PMID 34406595, 2021). "Taken together, those results suggest that combination therapy using bleomycin and MEK and/or ACE inhibitors could be beneficial for treating cancers, particularly basal-like type breast cancer." (PMID 33858332, 2021). "Several studies have suggested that commonly used medications such as β-blockers, angiotensin-converting enzyme (ACE) inhibitors, or statins may actually reduce breast cancer mortality." (PMID 32759815, 2020). "ACE acted as a therapeutic agent in a rat breast cancer model." (PMID 31826147, 2019). "In addition, the use of ACE inhibitors as co-therapies during breast cancer chemotherapy has been examined and found to be ineffective, further questioning the importance of this regulatory pathway in tumour development." (PMID 26813959, 2016). "Moreover, blockade of ACE and AT-1R significantly inhibited development of many tumour types (breast cancer, non-small cell pulmonary cancer, gastric cancer) and decreased the density of blood vessels as well as their metastatic potential." (PMID 22581182, 2012). "Future prospective studies analyzing expression of RAS components and AngII production in breast cancer may lead to the identification of a subpopulation of tumors that respond to ACE inhibitors and/or ARBs." (PMID 22536420, 2012).